CCND3 (cyclin D3)
Diseases named in the same sentence as CCND3 in open-access papers (continued):
Sharing a sentence is not in itself a finding about the gene and the disease.
Burkitt lymphoma (9 papers, 2007 to 2025). A rare form of malignant mature B-cell non-Hodgkin lymphoma. "Given the prevalence of D3 mutations in Burkitt’s lymphoma, it is striking that little is known about post-translational modification of cyclin D3." (PMID 33122824, 2021). "Cyclin D3 is overexpressed in specific human cancers and is subject to point mutations specifically in Burkitt’s lymphoma; the specific residue targeted, Thr-283 has been implicated in regulating cyclin D3 protein destruction." (PMID 33122824, 2021). "Cyclin D3 is overexpressed in ~50% of Burkitt’s lymphoma correlating with a mutation of Thr-283." (PMID 33122824, 2021). "•EBV-negative Burkitt lymphoma is more dependent on ID3/TCF3/CCND3 axis deregulation compared to EBV-positive Burkitt lymphoma." (PMID 41297313, 2025). "We assessed whether p38 affects cyclin D3 expression in CA46 Burkitt’s lymphoma cells." (PMID 33122824, 2021). "Mutations located at the 260–290 amino acids of CCND3 are found both in Burkitt lymphoma and DLBCL, which is likely to increase the stability of cyclin D3, and to further promote cell cycle progression." (PMID 35303910, 2022). "We confirmed that Fbxl8 forms an SCF complex in vivo and in vitro and subsequently demonstrated that endogenous Fbxl8 binds to cyclin D3 in NIH3T3 cells and Burkitt’s lymphoma, Raji cells." (PMID 33122824, 2021). "As expected, mutations in frequent drivers such as CREBBP, KMT2D,TNFRSF14 and RRAGC were more frequent among follicular lymphomas, those of MYC, CCND3 and ID3 prevailed among Burkitt lymphoma and those of BTG2, PIM1, SGK1 and SOCS1 were more frequent among DLBCL." (PMID 33945543, 2021).
colorectal cancer (9 papers, 2018 to 2025). A primary or metastatic malignant neoplasm that affects the colon or rectum. "Several genes with high-frequency and important CNVs, namely, MYC, FGFR1, CCNE1, and CCND3 have been observed in lung and colorectal cancer samples." (PMID 35402275, 2022). "While the expression of Ccnd3 was not statistically significantly associated with the prognosis of colorectal cancer." (PMID 40084254, 2025). "In addition, treatment with hydroxydibenzoylmethane, an apoptosis inducer, stimulated cyclin D3 expression in human colorectal carcinoma cells." (PMID 35548329, 2022). "CCND2 and CCND3 were used as positive markers for cell cycle in colorectal cancer." (PMID 34548081, 2021). "Therefore, 4i mainly inhibited colorectal carcinoma growth in CDK 6/cyclin D3 dependent manner." (PMID 39487179, 2024).
myeloma (9 papers, 2016 to 2025). "Mutation of at least one out of five genes (cyclin D1, C-MAF, FGFR3/MMSET, cyclin D3 and MAFB) seems to be a consistent finding in plasma cell myeloma which requires about three such rate limiting steps on average to manifest clinically." (PMID 40720480, 2025). "Myeloma cells highly expressed well-known driver genes, including CCND1, NDS2/MMSET, CCND3 and pathway analysis showed prominent upregulations of multiple biological processes and pathways in myeloma cells compared with nPCs." (PMID 36717896, 2023). "Among the stable myeloma precursor condition cases, we identified only 11 SV hotspots: all translocations between the IGH locus and CCND1 (n = 7), MAFB (n = 2), CCND3 (n = 1), and LTBR|LAG3 (n = 1)." (PMID 33767199, 2021). "The key myeloma-initiating genetic events are hyperdiploidy and translocations involving the immunoglobulin heavy chain (IgH) enhancer on chromosome 14, which leads to the activation of oncogenes (e.g., CCND1, CCND3, MAF, and MMSET)." (PMID 35982976, 2022). "Other examples of translocation between IGH and other oncogenes are BCL2 in FL, BCL6 in diffuse large B cell lymphoma (DLBCL) and CCND1 (Cyclin D1), CCND3 (Cyclin D3), FGFR3/MMSET (Fibroblast growth factor receptor 3/multiple myeloma SET domain), and MAF (c-maf) in multiple myeloma (MM)." (PMID 28867784, 2017).
bladder cancer (7 papers, 2012 to 2022). "Another circRNA, hsa_circ_0002768 (circMYLK), was significantly upregulated and contributed to malignant development via targeting miR-34a to enhance the CCND3 expression in bladder cancer cells." (PMID 36360223, 2022). "In tumor subgroup, CCND3 revealed oncogenic role in bladder cancer (HR = 4.60, 95% CI: 1.89‐12.57, P = 0.894)." (PMID 30950241, 2019). "Accordingly, cyclin D3 and E expression levels have been shown to closely correlate with bladder cancer recurrence and progression." (PMID 31167517, 2019). "Urinary protein levels of FGFR3 and Cyclin D3 were analyzed by Western blotting in 321 bladder cancer follow-up patients and 150 healthy control samples." (PMID 30544619, 2018). "Meanwhile, CCND3‐positive expression was correlated with shorter DFS/RFS/PFS in bladder cancer." (PMID 30950241, 2019).
glioblastoma (7 papers, 2012 to 2022). The most malignant astrocytic tumor (WHO grade IV). "In glioblastoma cells, miR-195 could inhibit cell invasion by inhibiting CCND3 and cause cytoplasmic accumulation of p27." (PMID 22723898, 2012). "In GIST and glioblastoma, CCND3 has been shown to be a key target of miR-195-induced inhibition of cell invasion." (PMID 25300797, 2014). "In the glioblastoma cell line (T98G), we detected the overexpression of the Cyclin D3 transcript." (PMID 36142793, 2022). "Top hub nodes from glioblastoma multiforme networks contain six matches, namely cyclin dependent kinase 2 (CDK2), cyclin A2 (CCNA2), cyclin B1 (CCNB1), erb-b2 receptor tyrosine kinase 2 (HER2), cyclin E1 (CCNE1), and cyclin D3 (CCND3)." (PMID 31952211, 2020).
glioma (7 papers, 2006 to 2025). A benign or malignant brain and spinal cord tumor that arises from glial cells (astrocytes, oligodendrocytes, ependymal cells). "Furthermore, the uncontrolled growth of gliomas can be driven by frequent mutation and transcriptional dysregulation of cell cycle factors, such as cyclin D3 encoded by CCND3, and involved in the control of G1/S phase transition." (PMID 39267734, 2024). "The full complete coding sequences of c-Myc and CCND3 mRNAs were shown to be encapsulated in glioma-derived EVs." (PMID 39267734, 2024). "As analysed in the same cyclin D3 co-immunoprecipitations in T98G glioma cells, serum stimulates the activating phosphorylation of CDK4 but not that of the related CDK6." (PMID 17092340, 2006). "Zeng and colleagues have shown that c-Myc and CCND3 mRNAs were encapsulated in glioma MVs." (PMID 39267734, 2024). "In T98G glioma cells, serum stimulates the phosphorylation of cyclin D3-bound CDK4 but not cyclin D3-bound CDK6." (PMID 17092340, 2006). "Five out of the ten top hub nodes from general glioma networks from StringDB and BioGRID are matching genes containing erb-b2 receptor tyrosine kinase 2 (HER2), erb-b2 receptor tyrosine kinase 4 (HER4), cyclin D3 (CCND3), TEK tyrosine kinase (TEK), and transforming growth factor alpha (TGFA)." (PMID 31952211, 2020).
B-cell lymphomas (6 papers, 2015 to 2025). "Multiple B-cell lymphomas have been reported to show gene mutations in the CCND3." (PMID 38179383, 2023). "A study examined the presence of cyclin D3 in splenic B-cell lymphoma and found that 24 out of 33 cases of splenic diffuse red pulp small B-cell lymphomas (SDRPBLs) expressing cyclin D3." (PMID 38179383, 2023). "In the other types of splenic B-cell lymphomas that were examined, cyclin D3 expression was infrequent." (PMID 38179383, 2023). "Immunohistochemistry for cyclin D3 is a promising marker as it is reported to be expressed in approximately 70% of SDRPLs and not in other splenic B-cell lymphomas, but the current data are still limited." (PMID 37656249, 2023). "CCND3/IGH translocations resulting in cyclin D3 overexpression have previously been documented in other B-cell lymphomas, but no CCND3 translocations were detected using a CCND3 Break Apart FISH Probe Kit." (PMID 35158965, 2022).
breast tumors (6 papers, 2008 to 2025). "Human breast tumors also have lower levels of LPP1 and higher levels of cJUN, cFOS, MMP-1, -7, -8, -9, -12, -13, cyclin D1, and cyclin D3 relative to normal breast tissue." (PMID 31534541, 2019). "These human breast tumors had higher content of cFOS, cJUN, FRA1, cyclin D1 and cyclin D3 compared to normal breast tissue." (PMID 31534541, 2019).
diffuse large B-cell lymphoma (6 papers, 2017 to 2024). "Diffuse large B-cell lymphoma (DLBCL) is the most common form of non-Hodgkin’s lymphoma, and alterations in the cyclin D/CDK4-6 pathway are found in approximately 67% of DLBCL cases, with CCND3 overexpression accounting for 53%." (PMID 37510349, 2023).
non-small cell lung carcinoma (6 papers, 2018 to 2025). A group of at least three distinct histological types of lung cancer, including non-small cell squamous cell carcinoma, adenocarcinoma, and large cell carcinoma. "Interestingly, in a KRAS-driven non-small cell lung cancer mouse model, ERK-induced concomitant upregulation of Ccnd1, as well as Ccnd3, was observed, rendering the tumor resistant to palbociclib." (PMID 35013097, 2022).
osteosarcoma (6 papers, 2014 to 2025). A usually aggressive malignant bone-forming mesenchymal neoplasm, predominantly affecting adolescents and young adults. "CCND3 amplifications were mainly identified in osteosarcoma patients, with 42/43 CCND3 mutations identified being in the 227 osteosarcoma patients present in the cohort (42/227, 18.5%)." (PMID 37510349, 2023). "By comparing the ages of patients, it was found that CCND3 mutations were more frequent in paediatric, adolescent, and young adult (P-AYA) osteosarcoma than in adult osteosarcoma." (PMID 37510349, 2023). "We sought to detect chimeric KCNMB4-CCND3 and LRP1-SNRNP25 protein products in 31 human osteosarcoma tissues by western blotting with antibodies against CCND3, KCNMB4, SNRNP25 and LRP1." (PMID 25300797, 2014). "Since LRP1 and CCND3 play important roles in regulating tumor cell migration, invasion, proliferation and apoptosis in other cancers, we set out to test whether the chimeric proteins might play any role in osteosarcoma cells." (PMID 25300797, 2014). "In particular, CNV was more frequent in CCND3, AURKB, CCNE1, GID4, and MYC in P-AYA, while MDM2, CDKN2A/B, and FRS2 were more frequently altered in adult osteosarcoma (p < 0.001)." (PMID 35705558, 2022). "A recurrent fusion gene between KCNMB4 and CCND3 has also been identified in a cohort of osteosarcoma, but not in a cohort of 240 other sarcomas, further suggesting a specific role of CCND3 in osteosarcoma." (PMID 37510349, 2023).
acute myeloid leukemia (5 papers, 2008 to 2023). Acute myeloid leukemia (AML) is a group of neoplasms arising from precursor cells committed to the myeloid cell-line differentiation. "For example, the gene encoding the Cyclin D3 (CCND3) was differentially expressed following overexpression of the CBF complex and mutations in this gene have been described in acute myeloid leukemia patients." (PMID 18671852, 2008). "It was previously shown that DYRK1A phosphorylates c-Myc in acute myeloid leukemia (AML), and Cyclin D3 in pre-B cells to enhance their degradation." (PMID 36927854, 2023).
gastric cancer (5 papers, 2016 to 2025). A primary or metastatic malignant neoplasm involving the stomach. "CCT3 augments the viability of gastric cancer cells by modulating cell cycle proteins, including mitogen-activated protein kinase 7, cyclin D3, and cyclin-dependent kinases." (PMID 35773623, 2022). "We found that the expression of β-catenin and its downstream targets CD44, c-MYC, and Cyclin-D3 were significantly up-regulated in gastric cancer cells after treatment with low level of DIM." (PMID 26918831, 2016). "Amplifications of ERBB2 and CCND3 were significantly more frequent in ELF3/HNF4A up-regulated gastric cancers (28.6% and 20.4%, respectively) compared with the group of non-up-regulated cancers (2.4% and none, Student’s t-test p = 0.0006 and 0.001, respectively)." (PMID 41425714, 2025). "Our results suggest that miR-375 can induce G1 cell cycle arrest by inhibiting cyclin D1, cyclin D3, and the phosphorylation of Rb in AGS and MKN-28 gastric cancer cells." (PMID 27689991, 2016). "Our results indicated that the overexpression of miR-375 inhibited the expression of cyclin D1 and cyclin D3 and the phosphorylation of Rb in AGS and MKN-28 human gastric cancer cells." (PMID 27689991, 2016).
pancreatic cancer (5 papers, 2010 to 2024). "Our data suggest that CCND1 and CCND3 associate with unique Rb phosphorylation patterns to mediate a differential effect on global gene transcription in pancreatic cancer cells." (PMID 20113529, 2010). "In accordance, the marked decrease of Cyclin D3 protein levels and increase of p27 protein contents that are detected in all three cell lines strongly suggest a common mechanism of TH301 action in pancreatic cancer cells of diverse mutational composition." (PMID 39796036, 2024). "For instance, in pancreatic cancer cells, inhibition of cyclin D3 suppresses proliferation to a greater extent compared to cyclin D1 inhibition." (PMID 35406445, 2022).
prostate carcinoma (5 papers, 2014 to 2025). A carcinoma that arises from epithelial cells of the prostate gland.
thyroid cancer (5 papers, 2019 to 2025). "In thyroid cancer tissues with high KAT8 expression, KAT8 knockdown decreased the levels of cyclin D1 (CCND1) and D3 (CCND3), critical regulators of the G1/S transition, resulting in G1-phase cell cycle arrest and suppressed thyroid cancer cell proliferation." (PMID 40508066, 2025). "In addition, Cyclin D3 played an important role in regulation of cancer cell growth and glycolysis, and we found the levels of cyclin D3 were increased in thyroid cancer tissue, and positively related with the levels SGLT2 in GEO and TCGA dataset." (PMID 35148777, 2022). "Interestingly, our result revealed the levels of SGLT2 were positively related with cyclin D3 in thyroid cancer patients." (PMID 35148777, 2022). "In thyroid cancer patients, SGLT2 was increased in thyroid cancer and positively related to cyclin D3." (PMID 35148777, 2022). "Furthermore, canagliflozin inhibited G1/S phase transition and cyclin D1, cyclin D3, cyclin E1, cyclin E2, and E2F1 expression levels in thyroid cancer cell." (PMID 35148777, 2022).
acute lymphoblastic leukemia (4 papers, 2019 to 2022). Leukemia with an acute onset, characterized by the presence of lymphoblasts in the bone marrow and the peripheral blood. "The role of CCND3 was extensively investigated in T-cell acute lymphoblastic leukemia (T-ALL)." (PMID 35013097, 2022). "This includes a pro-survival activity of cyclin D3/Cdk6 activity attributed to its phosphorylation and inhibition of glycolytic enzymes, phosphofructokinase (PFKP) and PKM2, in T acute lymphoblastic leukemia (T-ALL) cells and other tumors with high expression of Cdk6." (PMID 35670764, 2022).
anemia (4 papers, 2013 to 2020). A reduction in the number of red blood cells, the amount of hemoglobin, and/or the volume of packed red blood cells. "For example, studies on cyclin D3 KO mice showed that 0.7 fewer cell divisions per cell during terminal differentiation led to anaemia." (PMID 26095538, 2015). "Additionally, CCND3 knockout mice show increased prevalence of heart abnormalities and severe anemia." (PMID 24023702, 2013). "More severe anemia and increased myeloid infiltration and destruction of the spleen contributed to the earlier death of these mice, and elevated p-AKT, cyclin D1, and cyclin D3 might contribute to the development of this phenotype." (PMID 27366593, 2015). "CCND3 null mice are viable and fertile and do not show important signs of anemia." (PMID 32528964, 2020).
liver cancer (4 papers, 2021 to 2024). An epithelial or non-epithelial malignant neoplasm that arises from the liver. "Also, miR-194 inhibited key liver cancer phenotypes by modulating PTBP1/CCND3 signaling." (PMID 34716285, 2021). "The therapeutic approach with targeting liver proliferation is also supported by several reports showing that cell cycle proteins CDK4, Cyclin D3, E2F1, and liver cancer promoting protein Gankyrin play a critical role in development of NAFLD." (PMID 37967813, 2024).
lung adenocarcinoma (4 papers, 2018 to 2025). A carcinoma that arises from the lung and is characterized by the presence of malignant glandular epithelial cells. "The gene expression levels of Ki67, MCM2, CDC20, and CCND3 in tumor tissues from lent-miR-138-5p treated A549 lung adenocarcinoma tumor-bearing mice were lower than those of the other groups." (PMID 32754587, 2020). "Analysis of gene expression in TCGA NSCLC patients shows that CCND3 is expressed at slightly lower levels in tumor tissues compared to adjacent normal tissues in lung adenocarcinoma (LUAD) patients and lung squamous cell carcinoma (LUSC) patients." (PMID 29416000, 2018). "In this study, we found that CCND3 was downregulated in cisplatin-resistant (cis-diamminedichloroplatinum, DDP) lung adenocarcinoma (LUAD) cells." (PMID 39781469, 2025).
neuroblastoma (4 papers, 2016 to 2024). Neuroblastoma (NB) is the most common solid, extracranial childhood tumor. "Huaier extract induced cell cycle arrest at G0/G1 phase in neuroblastoma and decreased the cell cycle related protein expression of cyclin D3." (PMID 33456359, 2021). "Isotretinoin-mediated neuroblastoma cell differentiation is orchestrated by targeting MYCN, cyclin D3, and Wnt10B." (PMID 38249515, 2023).
bone tumor (3 papers, 2012 to 2023). "High-level amplification of TGFβ2 (1q41), CCND3 (6p21), WI-6509 (11qtel), SHGC-5557 (12ptel), TCL1A (14q32.1), CREBBP (16q13.3), HIC1 (17p13.3), THRA (17q11.2), AFM217YD10 (17qtel), LAMA3 (18q11.2), RUNX1 (21q22.3) and D22S543 (22q11), was commonly observed in aggressive bone tumors." (PMID 23199169, 2012).
mantle cell lymphoma (3 papers, 2022 to 2025). Mantle cell lymphoma is a rare form of malignant non-Hodgkin lymphoma affecting B lymphocytes in the lymph nodes in a region called the ``mantle zone''. "CCND2 and CCND3 rearrangements detected in most cyclin D1-negative mantle cell lymphoma represent a recurrent disease mechanism." (PMID 41374977, 2025). "In contrast, when investigating 74 SMZL, 35 mantle cell lymphoma (MCL), 7 HCL and 40 CLL, cyclin D3 was considered to be positive in only 4 patients (1 SMZL, 1 HCL and 2 MCL)." (PMID 36620555, 2022).